ABCC1 (ATP binding cassette subfamily C member 1 (ABCC1 blood group))
Description:
Mediates export of organic anions and drugs from the cytoplasm. Mediates ATP-dependent transport of glutathione and glutathione conjugates, leukotriene C4, estradiol-17-beta-o-glucuronide, methotrexate, antiviral drugs and other xenobiotics. Confers resistance to anticancer drugs by decreasing accumulation of drug in cells, and by mediating ATP- and GSH-dependent drug export. Hydrolyzes ATP with low efficiency. Catalyzes the export of sphingosine 1-phosphate from mast cells independently of their degranulation. Participates in inflammatory response by allowing export of leukotriene C4 from leukotriene C4-synthesizing cells (By similarity). Mediates ATP-dependent, GSH-independent cyclic GMP-AMP (cGAMP) export. Thus, by limiting intracellular cGAMP concentrations negatively regulates the cGAS-STING pathway. Exports S-geranylgeranyl-glutathione (GGG) in lymphoid cells and stromal compartments of lymphoid organs. ABCC1 (via extracellular transport) with GGT5 (via GGG catabolism) establish GGG gradients within lymphoid tissues to position P2RY8-positive lymphocytes at germinal centers in lymphoid follicles and restrict their chemotactic transmigration from blood vessels to the bone marrow parenchyma (By similarity). Mediates basolateral export of GSH-conjugated R- and S-prostaglandin A2 diastereomers in polarized epithelial cells.
Synonyms: MRP; MRP1; GS-X; ABC29; ABCC; DFNA77
Tractability: Small molecule: a drug acting on it is in phase 2 or 3 trials; a structure with a bound ligand is known; a high-quality ligand is known; it belongs to a druggable protein family. Antibody: UniProt places it where antibodies can reach, with high confidence; its Gene Ontology location is reachable by antibodies, with high confidence; UniProt predicts a signal peptide or a membrane-spanning region; the Human Protein Atlas places it where antibodies can reach. PROTAC: ubiquitination databases record sites on it; its protein half-life has been measured; a small molecule that binds it is known.
Target class: ABCC subfamily; ATP-binding cassette; Transporter; Primary active transporter
Chemical probes: Dexverapamil, MITOXANTRONE
Safety:
Unwanted effects reported when the protein is acted on. In parentheses: how it was acted on, where the effect was seen, and who reports it.
cardiotoxicity (source: ClinPGx)
drug toxicity (source: ClinPGx)
have a reduction in psoriasis area or disease severity (source: ClinPGx)
neutropenia (source: ClinPGx)
reduction in psoriasis area or disease severity (source: ClinPGx)
Gene: Protein-coding gene on chromosome 16 (15,949,138 to 16,143,257, forward strand). Ensembl gene ENSG00000103222.
Subcellular location: Cell membrane; Basolateral cell membrane
Subcellular location (Human Protein Atlas): Plasma membrane; Cell Junctions
Pathways (Reactome):
Metabolism: Heme degradation; Sphingolipid de novo biosynthesis; Synthesis of Leukotrienes (LT) and Eoxins (EX); Transport of RCbl within the body
Cellular responses to stimuli: Cytoprotection by HMOX1; NFE2L2 regulating MDR associated enzymes
Drug ADME: Paracetamol ADME
Transport of small molecules: ABC-family protein mediated transport
Gene Ontology:
Molecular function: ABC-type transporter activity; ABC-type vitamin B12 transporter activity; ABC-type xenobiotic transporter activity; ATPase-coupled lipid transmembrane transporter activity; carboxylic acid transmembrane transporter activity; efflux transmembrane transporter activity; xenobiotic transmembrane transporter activity; ABC-type glutathione S-conjugate transporter activity; ATPase-coupled transmembrane transporter activity; glutathione transmembrane transporter activity; ATP binding; ATP hydrolysis activity; transmembrane transporter activity
Biological process: carboxylic acid transmembrane transport; cyclic nucleotide transport; export across plasma membrane; phospholipid translocation; sphingolipid translocation; transepithelial transport; xenobiotic transport across blood-brain barrier; cell chemotaxis; cellular response to amyloid-beta; cellular response to oxidative stress; cobalamin transport; glutathione transmembrane transport; heme catabolic process; leukotriene metabolic process; leukotriene transport; positive regulation of inflammatory response; response to xenobiotic stimulus; sphingolipid biosynthetic process; transmembrane transport; transport across blood-brain barrier; xenobiotic metabolic process; xenobiotic transport; carboxylic acid transport
Cellular component: apical plasma membrane; basal plasma membrane; basolateral plasma membrane; cell junction; extracellular exosome; lateral plasma membrane; membrane; plasma membrane
Genetic constraint (gnomAD): Loss-of-function variants: 80 observed, 170.83 expected, observed/expected ratio (o/e) 0.47, 90% interval 0.39 to 0.56. The upper end of that interval is the gene's LOEUF score, 0.56, which puts it in group 2 of 6, group 1 being the genes least tolerant of losing a copy. Missense variants: 1,763 observed, 2,012.6 expected, observed/expected ratio (o/e) 0.88, 90% interval 0.84 to 0.91. Synonymous variants: 909 observed, 834.95 expected, observed/expected ratio (o/e) 1.09, 90% interval 1.03 to 1.15.
Gene-disease validity (ClinGen):
ClinGen rates the evidence that ABCC1 causes each of these diseases.
autosomal dominant nonsyndromic hearing loss (autosomal dominant): Limited. Autosomal dominant form of nonsyndromic deafness.
Homologues: Orthologues: chimpanzee ABCC1 (99% identical), macaque ABCC1 (98% identical), pig ABCC1 (90% identical), guinea pig ABCC1 (90% identical), rabbit ABCC1 (88% identical), mouse Abcc1 (88% identical), rat Abcc1 (87% identical), dog ABCC1 (87% identical), tropical clawed frog abcc1 (75% identical), zebrafish abcc1 (70% identical), Drosophila melanogaster MRP (50% identical), Drosophila melanogaster rdog (30% identical), and 9 more. Paralogues in human: ABCC3 (57% identical), ABCC2 (48% identical), ABCC6 (45% identical), ABCC8 (32% identical), ABCC9 (32% identical), ABCC5 (32% identical), ABCC4 (32% identical), ABCC10 (31% identical), ABCC12 (29% identical), ABCC11 (27% identical), CFTR (24% identical).
Diseases named in the same sentence as ABCC1 in open-access papers:
ABCC1 is named in the same sentence as 145 diseases in open-access papers, as found by Europe PMC text mining. Sharing a sentence is not in itself a finding about the gene and the disease. The quoted sentences say what the papers report.
breast carcinoma (111 papers, 2011 to 2025). "To investigate the potential involvement of other ABC transporters associated with breast cancer chemoresistance, we analysed the expression of ABCC1, ABCC3, and ABCG2." (PMID 39858449, 2025). "This study provided evidence that ABCC1 rs4148350 significantly increases the risk of early AIC in patients with breast cancer." (PMID 37367397, 2023). "(2013), reported the association of three variants in the ABCC1 gene with hematologic toxicity during chemotherapy in a Belgian population of women with breast cancer." (PMID 38269022, 2023). "A tissue microarray analysis conducted on 281 breast cancer patients revealed that shorter disease free-survival was significantly associated with ABCC1 and ABCC11 expressions." (PMID 27171227, 2016). "Analogously with the ABCB1/P-glycoprotein, in the present study, we have observed associations between genetic variability in ABCC1 and its transcript levels in tissues from breast cancer patients." (PMID 25078270, 2014). "Multidrug resistance-associated protein 1 coded by the ABCC1 gene has recently been suggested as a potential prognostic marker in breast cancer patients." (PMID 25078270, 2014). "Very recently convincing association between rs4148350, rs45511401, and rs246221 SNPs in ABCC1 and risk of febrile neutropenia in breast cancer patients treated by 5-fluorouracil, epirubicin and cyclophosphamide (FEC regimen) has been shown." (PMID 25078270, 2014). "Additionally, IFP has been linked to increased resistance to doxorubicin in human breast cancer cells, mediated by the overexpression of ATP-binding cassette subfamily C member 1 (ABCC1)." (PMID 39849659, 2025). "Quite recently, based on the data from The Cancer Genome Atlas (TCGA), it was discovered that a variant burden in ABCC1 substantially predicts disease-free survival in breast cancer patients and that this significance was even stronger in cyclophosphamide- and doxorubicin-treated subgroups." (PMID 32872162, 2020). "Finally, we investigated the efflux of S1P, as levels of S1P have previously been implicated in breast cancer, and both ABCC1 and ABCC4 are capable of transporting S1P." (PMID 33081264, 2020). "Similarly, an association of ABCC1 expression with the survival of breast cancer patients was described." (PMID 33334016, 2020). "Distribution of ABCC1 SNPs and allele frequencies in breast cancer patients." (PMID 25078270, 2014). "A recent study in a cohort of 179 patients with breast cancer identified higher expression of both ABCB1 and ABCC1 as associated with shorter duration of T-DXd treatment, and ABCB1 was also associated with shorter T-DXd-specific OS30." (PMID 41422323, 2025). "Specifically, ABCA1 (a major transporter of lipids out of cells), ABCB1, and BCRP are key players in breast cancer chemoresistance, and ABCB1 and ABCC1 are important indicators of breast cancer prognosis." (PMID 40869256, 2025). "Another study found that breast cancer cells grown on collagen I and fibronectin exhibited resistance to doxorubicin through upregulating ABCC1." (PMID 39123364, 2024). "ABCC1 expression was elevated to a larger extent in doxorubicin-resistant breast cancer samples than in doxorubicin-sensitive breast cancer tissues, and it was highly upregulated in MCF-7/ADR cells." (PMID 38413011, 2024). "Forced expression of ABCC1 confers chemoresistance in various tumor cell types, such as breast carcinoma and colon carcinoma." (PMID 39201428, 2024). "Studies have demonstrated that the restoration of miR-34a-5p expression significantly suppresses ABCC1 by directly targeting its 3′ untranslated region, leading to increased doxorubicin influx in resistant breast cancer cells." (PMID 39679367, 2024). "All these findings suggest that miR-134 downregulation promotes doxorubicin resistance in breast cancer and that the process is mediated through the regulation of the ABCC1 gene, which should be further explored in a therapeutic setting." (PMID 38413011, 2024).
breast carcinoma (continued). "Preclinical in vitro models of breast cancer cells exhibiting ABCC1 (multidrug resistance protein 1) expression exhibited 256-fold increased resistance to T-DM1 after three months of cyclical treatment." (PMID 37631232, 2023). "ABCC1 has been shown to be overexpressed in breast carcinoma and was correlated with poor prognosis and chemotherapeutic sensitivity." (PMID 36732567, 2023). "In conclusion, our results demonstrated that TM plays a suppressive role in the progression and metastasis of ER+ breast cancer, and it regulates curcumin sensitivity by interfering with ABCC1, LRP1, and MDR1 gene expression." (PMID 37239055, 2023). "Our results demonstrated a significant increment of ABCC1 protein expression during EMT, confirming previous data demonstrating an induction of ABCC1 mRNA levels after TGF-β treatment in breast cancer cells." (PMID 37047018, 2023). "Accumulating evidence suggests that the higher expression of ABCC1 is related to drug resistance and poor survival of lung and breast cancer patients." (PMID 37239055, 2023). "We aimed to determine the link between ABCB1 rs1045642, ABCC1 rs4148350, and ABCC1 rs3743527 and cardiotoxicity in breast cancer." (PMID 37367397, 2023). "Overexpression of cell surface efflux ABC transporters, including ABCB1, ABCC1, and ABCG2, was associated with chemoresistance in breast cancer." (PMID 37397367, 2023). "A recent study has also shown that increased export of S1P via ABCC1 enhances the transcription of SPHK1 resulting in more S1P formation in human MCF-7 breast cancer cells." (PMID 36309544, 2022). "In breast cancer cell lines, Notch-1 signaling induced by doxorubicin promoted ABCC1 overexpression." (PMID 35163586, 2022). "Clinical studies show that ABCC1 is upregulated in nonsmall cell lung cancer, breast cancer, ovarian cancer, renal cancer, and liver cancer, which is positively correlated with clinical–pathological stage and metastasis." (PMID 35938176, 2022). "Similar observations were reported in an earlier study, where export of S1P via ABCC1 was found to amplify the S1P axis involved in breast cancer progression and metastasis." (PMID 36309544, 2022). "Similar to our findings, high levels of ABCC1 in lymph node positive patients were suggestive of their potential role in breast cancer metastasis." (PMID 36309544, 2022). "In breast cancer cell lines, doxorubicin induced Notch-1 signaling which led to increased ABCC1 expression." (PMID 35163586, 2022). "Another recent study in breast cancer found that expression level of ABCC1 in tumor tissue of patients responding to chemotherapy was significantly lower compared to non-responding patients." (PMID 36309544, 2022). "With the presence of numerous binding sites, ABCB1 and ABCC1 can bind to and pump out a variety of chemotherapeutic drugs, such as Dox in breast cancer; paclitaxel and olaparib in ovarian cancer; and imatinib in chronic myelogenous leukemia." (PMID 34208283, 2021). "A higher staining intensity of ABCC1 was observed in lymph node metastasis than in the primary tumours of breast cancer patients." (PMID 33801148, 2021). "ABCC1 overexpression has been detected in various solid cancer types, including small cell lung carcinoma, prostate and breast cancer as well as childhood neuroblastoma, but also in hematological malignancies." (PMID 33066132, 2020). "It has been reported that ABCC1 is frequently expressed in lymph node metastases of breast cancer patients and that MRP1 expression is more pronounced in lymph node metastases than in corresponding primary tumors." (PMID 33081264, 2020). "The overexpression of the transporters, such as ABCB1, known as P-glycoprotein, P-gp, ABCG2, known as breast cancer resistant protein, BCRP, and ABCC1, known as multidrug resistance-associated protein 1, MRP1, contributes to MDR." (PMID 32365495, 2020).
breast carcinoma (continued). "In summary, our results show that ABCC1 plays a role in breast cancer proliferation, whilst ABCC4 has a greater role in cellular migration and invasion." (PMID 33081264, 2020). "In another breast-cancer study, high expression of ABCC1 and low expression of ABCC8 were found to be more strongly associated with high-grade breast cancer than with the less-aggressive grades I and II51." (PMID 32587767, 2020). "Following chemotherapeutic treatment, the expression of ABCC1 in breast cancer tumors was found to increase, and its expression level was shown to be highest in the most aggressive subtypes of breast cancers." (PMID 33081264, 2020). "Our results suggest that ABCC1 is important for breast cancer proliferation, whilst ABCC4 has a greater role in cellular migration and invasion." (PMID 33081264, 2020). "In the present study, single nucleotide polymorphisms (SNPs) from the ABCC1, ABCC2, ABCB1, and ABCG2 genes were screened in breast cancer patients and healthy volunteers from the Jordanian-Arab population." (PMID 31391850, 2019). "As reported, multidrug resistance-associated protein 1 (MRP1, also known as ABCC1) expression level was closely correlated with adverse chemotherapy outcomes in various cancers, including breast cancer, acute myeloid leukemia and non-small cell lung cancer." (PMID 31582906, 2019). "Doxorubicin induced Notch-1 signaling in breast cancer cell lines, which led to increased ABCC1 expression." (PMID 31443516, 2019). "A similar effect was reported for ABCC1, as the expression levels of the mRNA and protein were reduced in the miR-326 miRIDIAN mimic-transfected VP-16-resistant breast cancer cell line MCF-7/VP." (PMID 29401721, 2018). "Previous reports have exhibited ABCC1 to be up-regulated in colorectal cancer, lung cancer, and breast cancer." (PMID 29445446, 2018). "Due to incomplete data sets, promoters of PTEN and ABCC1 and breast cancer patients 1 and 18 were excluded in this evaluation." (PMID 28403857, 2017). "Due to incomplete data sets, promoters of PTEN and ABCC1 and breast cancer patients 1 and 18 were again excluded." (PMID 28403857, 2017). "The ABCC1 promoter was found to be hypomethylated in all tumor, tumor-adjacent and tumor-distant tissues from breast cancer patients as well as in breast tissues from healthy women." (PMID 27689338, 2016). "In breast cancers, ABCC1 expression has been correlated with patient survival following chemotherapy." (PMID 27171227, 2016). "Our data revealed that ABCC1 was overexpressed (p = 0.0056) in breast cancer tissue compared to normal, consistent with previous studies." (PMID 27171227, 2016). "In breast cancer, multidrug resistant proteins ATP-binding cassette transporters, ABCC1 and ABCG2, export S1P after estrogen stimulation of breast cancer cells." (PMID 26966342, 2016). "Consistent with this, we observed that treatment of breast cancer cell lines with anti-cancer agents increased their mRNA levels of both ABCC1 and ABCC3." (PMID 27171227, 2016). "Although the expression of ABCC1 in breast cancers has been investigated by multiple studies, the expression of ABCC3 has not yet been well investigated in grade III breast cancers." (PMID 27171227, 2016). "Together, our data is consistent with previous reports that have shown overexpression of ABCC1 in several cancers including breast cancers." (PMID 27171227, 2016). "Our data revealed that chemotherapy-treated breast cancer samples showed higher expression of ABCC1 compared to chemo-naive samples, similar to previous report." (PMID 27171227, 2016). "In this study, we have examined the expression of ABCC3 in breast cancers and studied its role in drug resistance and stemness of breast cancer cells in comparison with the more studied ABCC1." (PMID 27171227, 2016). "Overexpression of ABCC1 has been linked to MDR in small cell lung carcinoma, prostate and breast cancer as well as childhood neuroblastoma." (PMID 27689338, 2016).